INS (insulin)
Diseases named in the same sentence as INS in open-access papers (continued):
Sharing a sentence is not in itself a finding about the gene and the disease.
Insulin resistance (continued). "Our aim was to study whether glucose, insulin or insulin resistance are associated with episodic or semantic memory in a non-diabetic and non-demented population." (PMID 25798199, 2015). "Indeed, in mouse models, a loss of T-regulatory cells in adipose tissue accompanies the development of insulin resistance, with gain-of-function experiments improving insulin sensitivity, confirming the potential importance of T-regulatory cells in obesity-related insulin resistance." (PMID 25388403, 2015). "In brief, this figure shows that nitrate/nitrite could increase insulin secretion by increase pancreatic islet blood flow and activation of guanylyl cyclase and the cGMP pathway; nitrate/nitrite also improve insulin resistance and glucose uptake by increase gene expression of GLUT4." (PMID 25991919, 2015). "MVs derived from proinflammatory (M1) macrophages may, at least in part, contribute to the pathogenesis of obesity-induced insulin resistance, reducing insulin signal transduction and decreasing glucose uptake in human adipocytes, through NF-kappa B activation." (PMID 26064180, 2015). "Therefore, patients receiving exogenous insulin in the presence of insulin resistance may be repetitively exposed to high levels of insulin, which may trigger the mitogenic pathways leading to cancer in susceptible patients." (PMID 26171401, 2015). "Chronic insulin stimulation was shown to induce insulin resistance in mouse DRGs, as evidenced by decreased activation of Akt and its downstream effectors, and could attenuate the neurotrophic effects of insulin, resulting in mitochondrial dysfunction, subsequent development of PN." (PMID 25774226, 2015). "In the course of this study, it became apparent that the insulin-resistant animals fit the criteria for metabolic syndrome; however, the overarching goal of the study was to identify lipid-related events in the early stages of spontaneous insulin resistance development." (PMID 26063458, 2015). "Thus, TRPV1 agonists such as capsaicin may prevent brain insulin resistance by the activation of insulin/IGF-1 signaling." (PMID 25755673, 2015). "Interestingly, insulin has been shown to enhance Cd36 levels in skeletal and cardiac muscle; under a short term hyperinsulinemic-euglycemic clamp, insulin stimulated Cd36 levels in skeletal muscle, and the increase in Cd36 levels were positively correlated to insulin resistance." (PMID 26085100, 2015). "Insulin resistance (IR) development after twelve weeks feeding on high fructose and high fat diet was evidenced by the significantly higher weight gain (p < 0.01), glucose (p < 0.001), insulin (p < 0.05) and triglyceride (p < 0.05) levels in the IR group than those in the control group." (PMID 25889404, 2015). "However, it is not known whether this reduction is causative and precedes the other symptoms or is a compensatory mechanism that is activated to ameliorate the effects of the reduced insulin secretion and the increased insulin resistance." (PMID 25822220, 2015). "Mitochondrial abnormalities have been documented in insulin-resistant and diabetic states in human and animal studies, and it has been proposed that mitochondrial dysfunction may be the primary defect in obesity-related insulin resistance." (PMID 26035391, 2015). "In insulin resistance, cells do not respond to insulin, causing high blood sugar." (PMID 25734565, 2015). "Therefore liver enzyme elevation per se is not an indicator of decreased insulin sensitivity but a general metabolic deterioration along with insulin resistance in men, with no independent associations with the clamp M3 value." (PMID 25986611, 2015).
Insulin resistance (continued). "We stratified the subjects according to tertiles of insulin resistance (estimated by glucose clamp) and studied the highest (Group A: n=14) and the lowest (Group B: n=13) M-value tertiles, so that Group A and B, respectively, represented the less and more insulin-resistant groups." (PMID 26258766, 2015). "Therefore, other factors (e.g., hepatic and adipose tissue insulin resistance) atop of muscle insulin resistance may participate in the improvements in “whole-body” insulin sensitivity induced by regular exercise." (PMID 26172834, 2015). "It was suggested that insulin resistance to leptin in β-cells in glucose intolerance state, might prevent the inhibitory effect of leptin on insulin secretion resulting in hyperinsulinemia, which might exhaust pancreatic β-cells leading to development of NAFLD." (PMID 26569494, 2015). "Therefore, we can only speculate as to the true extent of the involvement of insulin‐mediated molecular mechanisms and how critical a role they represent in the accelerated process of atherosclerosis in individuals with insulin resistance and type 2 diabetes." (PMID 25138792, 2014). "Finally, one of the diagnostic criteria used in this study was based on arbitrary assumed cut values for HOMA-IR, which represents only a surrogate method for the assessment of insulin resistance, derived from a single measurement of fasting glucose and insulin." (PMID 24535466, 2014). "However, an elevated insulin concentration itself can induce or exacerbate insulin resistance." (PMID 25259572, 2014). "In addition, early-morning fasting insulin, homeostasis model assessment of insulin resistance (HOMA-IR), and insulin/glucose ratio (IGR) were higher in patients with aldosterone escape and high urinary aldosterone excretion, when compared to the healthy population." (PMID 25352918, 2014). "Furthermore, to examine whether serum zinc concentration was associated with the HOMA parameters, steady state beta cell function (%B), insulin sensitivity (%S) and insulin resistance (IR) for normoglycaemic and pre-diabetic groups were calculated." (PMID 24416185, 2014). "The higher S-TG might indicate (in addition to an increase in S-Glu) that insulin dependent glucose transport is affected and the increased risk of metabolic syndrome with smoking may be associated with high S-TG but not linked to insulin resistance." (PMID 24636522, 2014). "However, there are suggestions that ethnicity may influence the performance of available surrogate indices of insulin sensitivity, particularly among populations with high prevalence of insulin resistance such as Africans." (PMID 25106496, 2014). "In the current study, ezetimibe ameliorated insulin resistance in mice fed the high-fat diet, and significantly altered fasting glucose in addition to glucose levels at 90 and 120 min of the ipGTT, which strongly indicated that ezetimibe improved insulin sensitivity." (PMID 25310357, 2014). "Although in some studies the increase in VAI was significantly associated with a significant reduction in insulin sensitivity, VAI is not to be seen as an index of insulin sensitivity, but as an indicator of altered adipose function which is associated with insulin resistance." (PMID 24829577, 2014). "Considering hormonal changes a stress-induced hyperactivity of the HPA axis may explain the association between stress and all elements of MES: first, excess amounts of glucocorticoids enhance hepatic gluconeogenesis and inhibit the secretion and action of insulin leading to insulin resistance." (PMID 24743684, 2014). "Excess fasting phosphorylation of muscle IRS‐1 at Ser636 may be a major cause of the insulin resistance seen in obesity and might prevent improvement in insulin responsiveness when exercise training is not accompanied by weight loss." (PMID 25472611, 2014).
Insulin resistance (continued). "Thus, the main homeostatic defect could be ascribed to age-dependent failure of the endocrine pancreas to provide enough insulin to overcome the state of increased peripheral insulin resistance." (PMID 25232350, 2014). "ENPP1 may contribute to insulin resistance through its inhibitory action on insulin signalling." (PMID 25539584, 2014). "Several mediators such as leptin, which reduces insulin-induced fatty acid oxidation and triacylglycerol synthesis, or fatty acids, which compete with glucose for their mitochondrial oxidation, are commonly suggested as contributors of insulin resistance and glucose intolerance." (PMID 25142225, 2014). "Furthermore, since prediabetic individuals usually exhibit increased insulin resistance, this type of Ramadan fasting could deteriorate their insulin sensitivity further, hence accelerating their progression to type 2 diabetes." (PMID 24810091, 2014). "Epidemiological studies have suggested that leptin regulates total body sensitivity to insulin and triglyceride levels in leptin-deficient individuals, and there is a negative relationship between insulin resistance and cerebrospinal fluid leptin concentrations." (PMID 24809394, 2014). "While long-term impacts of raisins on insulin control require furtherinvestigation, the present study suggests that raisins, through acute postprandialinsulin-sparing effects, may be a healthy food choice in patients with insulin resistance ordiabetes." (PMID 25191601, 2014). "Furthermore, while these studies were performed in mouse ESCs, we believe that the findings from this study can be used in future studies examining the role of insulin or Wnt signaling pathways in other biological settings, such as the study of insulin resistance in the diabetic brain." (PMID 25165462, 2014). "Hence, insulin resistance often is accompanied by increased circulating levels of insulin." (PMID 25486190, 2014). "In addition, new treatment paradigm, aimed at reducing insulin resistance may represent a more effective treatment to decrease insulin dose." (PMID 24650537, 2014). "Therefore, an IL‐6 paradox does exist, such that elevated IL‐6 can lead to the development of insulin resistance, and yet may also lead to increased insulin sensitivity." (PMID 24997069, 2014). "First, does glucose itself cause insulin resistance in the absence of insulin?" (PMID 24741073, 2014). "Therefore, the purpose of the present study was to investigate possible correlations between apelin-12 levels and obesity in children in China and identify associations between apelin-12 and obesity-related markers, including lipids, insulin sensitivity and insulin resistance index." (PMID 24475149, 2014). "The glucose metabolism in human myotubes decreased upon simvastatin treatment, and it is tempting to speculate if this could contribute to hyperglycemia, since some patients taking statins develop decreased insulin sensitivity, insulin resistance and glucose intolerance." (PMID 24416446, 2014). "Upregulation of pathways for reactive oxygen species (ROS) production and oxidative stress in insulin-responsive tissues (liver and adipose tissue) has been observed before the onset of insulin resistance, which could be suppressed by dietary restriction or antioxidant supplementation." (PMID 24789994, 2014). "Therefore, previous studies have assessed whether the early administration of insulin to improve glucose control may result in improved insulin resistance and β-cell function." (PMID 24944613, 2014). "In addition, recent animal and in vitro evidence suggest that GH and insulin can share post-receptor signaling pathways, and these pathways may contribute to GH-induced insulin resistance." (PMID 24963636, 2014).
Insulin resistance (continued). "Early identification of pathogenic factors in the development of obesity related metabolic diseases such as insulin resistance, chronic inflammation, insulin secretion defect or adipose tissue dysfunction could result in personalized prevention or treatment strategies for individuals at high risk." (PMID 24968098, 2014). "Therefore, in addition to factors such as skeletal muscle mitochondrial dysfunction and skeletal muscle insulin signaling, which can exacerbate insulin resistance, factors determining beta cell function likely play a prominent role in the development of GDM and subsequent T2DM postpartum." (PMID 25216282, 2014). "However, we cannot exclude the possibility that the reduction in PINK1 levels, through inducing increased levels of basal insulin secretion, could contribute to the development of insulin resistance over time." (PMID 24806840, 2014). "However, as decreased expression of GLUT4 in adipose tissue likely leads to insulin resistance in other organs, insulin signaling and uptake of 2-deoxyglucose in multiple tissues, including muscle and liver, could be assessed in future studies." (PMID 25233471, 2014). "For treatment, the usual species of combination drug treatment of type II DM were sulfonylureas and the class of thiazolidinediones (TZD), which may directly decrease insulin resistance by enhancing insulin action within the skeletal muscle, liver, and adipose tissue." (PMID 25024728, 2014). "Furthermore, insulin resistance may be several orders of magnitude lower in newborns than in adults, which suggests a state of higher insulin sensitivity in utero." (PMID 25374599, 2014). "In states of insulin resistance, an inhibitory role of insulin on apoCIII expression may be lost." (PMID 25553059, 2014). "This relationship involves two main defects: insulin resistance (i.e., decreased capacity of insulin to stimulate glucose uptake in insulin-dependent tissues and to suppress endogenous glucose release, mainly from the liver) and β cell dysfunction resulting in decreased insulin secretion." (PMID 25152774, 2014). "Additionally, oxidative stress biomarkers have been shown to be increased in individuals who exhibit insulin resistance or insulin secretion impairment, indicating a positive correlation between oxidative stress and insulin resistance and insulin secretion impairment." (PMID 25019091, 2014). "Therefore, dysregulation of GSK-3β could result in attenuating insulin signaling, which was thought to induce insulin resistance." (PMID 25157753, 2014). "As insulin resistance can develop in the presence of inflammation or as a result of alterations in counter regulatory hormones that affect insulin, HP may thus promote insulin resistance by inducing chronic inflammation and affecting insulin-regulating gastrointestinal hormones." (PMID 25405220, 2014). "AC6 improved insulin sensitivity through the enhancement of insulin action on insulin receptor substrate-1 (IRS-1) associated phosphoinositide 3-kinase (PI3-kinase) and glucose transporter type 4 (GLUT4) activities in the muscles of animals exhibiting insulin resistance." (PMID 25396726, 2014). "Three of these genes have unknown function (RBMS1, PTPRD, and SRR), while RPS12, LIMK2, and AUH are associated with diabetic nephropathy, C2CD4A is associated with β-cell dysfunction, SPRY2 is associated with obesity and insulin resistance, and SASH1 is associated with insulin growth factors." (PMID 24744783, 2014). "Thus, at 8 weeks of age, male and female Crh−120/+ mice had significantly elevated plasma insulin concentrations after a 4-hour fast, and this hyperinsulinemia persisted at 12 and 16 weeks of age, consistent with likely insulin resistance due to increased adiposity." (PMID 24302625, 2014).
Insulin resistance (continued). "Moreover, an association was found between smoking status and insulin sensitivity in the normoglycaemic group indicating that current smokers had lower insulin sensitivity (P = 0.004) and that insulin resistance increases with an increase in the number of medications (p = 0.02)." (PMID 24416185, 2014). "Insulin stimulates the synthesis of glycogen, lipids and protein in the liver and suppresses hepatic glucose production by inhibiting gluconeogenesis, thus controlling blood glucose and lipid homeostasis, therefore hepatic insulin resistance generates hyperglycemia." (PMID 25069836, 2014). "Based on the strong correlation between increased lipid consumption and insulin resistance, some have suggested that the accumulation of cytoplasmic lipid intermediates that are often seen in diabetic patients and animal models directly impairs insulin signaling." (PMID 25152047, 2014). "Inositol is a polyol which may be considered a second messenger of insulin, and myo-inositol is one of its nine isomers, capable of reducing insulin resistance, blood pressure, and improving lipid profile in a small cohort of postmenopausal women affected by metabolic syndrome." (PMID 25254044, 2014). "Indeed, it modulates the expression of several genes with a crucial role in glucose, lipid and cholesterol metabolism, insulin signaling, and adipokines' production, whose imbalance leads to insulin resistance, obesity, type 2 diabetes, and cardiovascular diseases." (PMID 24790595, 2014). "Glycyrrhizin has been shown to could ameliorate insulin resistance, dyslipidemia in fructose-induced metabolic syndrome in rat model including decreased the enhanced levels of blood glucose, insulin and lipids and displayed elevated skeletal muscular GLUT4 proteins." (PMID 25375187, 2014). "Interestingly, the various measures of glycemia and insulin sensitivity did not associate with BMI, suggesting that general fat accumulation played no significant role in the observed insulin resistance in the current study." (PMID 25587486, 2014). "Furthermore, high salt diet impairs insulin sensitivity only in hypertensive patients with salt-sensitivity but not in those with salt-resistance, suggesting that there is a pathogenetic link among hypertension, salt-sensitivity and insulin resistance." (PMID 24485020, 2014). "Secondly, does fat itself cause insulin resistance without insulin?" (PMID 24741073, 2014). "Insulin resistance in the adipose tissue, leading to increased demands on pancreatic β-cells to produce insulin could therefore contribute to the eventual hypoinsulinaemia and impaired glucose tolerance observed in the offspring of obese dams at 6 months of age." (PMID 24749062, 2014). "Taken together we speculate that the higher level of circulating insulin that we observed in Perk heterozygous mice during early postnatal development eventually lead to insulin resistance in older mice analogous to the progression of type 2 diabetes from compensation to de-compensation." (PMID 24915520, 2014). "An alternative hypothesis regarding the non-cell-autonomous importance of insulin action for health and survivorship posits that insulin resistance may be viewed in certain circumstances as a protective, or even beneficial, adaptation to aging- or diet-related increases in insulin levels." (PMID 25244225, 2014). "Therefore, detailed studies on the molecular mechanisms of insulin action in insulin-sensitive tissues will contribute enormously to better understand the paradigm of CIH-induced insulin resistance, and so the relationship between OSA and metabolic dysfunction." (PMID 25400585, 2014). "In addition, insulin resistance was determined with the insulin tolerance test (ITT)." (PMID 24705496, 2014). "Furthermore, insulin resistance may enhance muscle catabolism because insulin acts as a powerful signal for proteins anabolism." (PMID 24937121, 2014).